CD36 (CD36 molecule (CD36 blood group))
Diseases named in the same sentence as CD36 in open-access papers (continued):
Sharing a sentence is not in itself a finding about the gene and the disease.
Alzheimer disease (28 papers, 2004 to 2024). A progressive, neurodegenerative disease characterized by loss of function and death of nerve cells in several areas of the brain leading to loss of cognitive function such as memory and language. "In a murine model of Alzheimer’s disease, the microglial expression of CD36 was downregulated, while the pharmacological activation of CD36 was associated with increased Aβ clearance." (PMID 36310859, 2022). "The present study provides evidence that TREM2 is required for preventing loss of memory and learning in Alzheimer’s disease by regulating C/EBPα-dependent CD36 expression and the consequent Aβ phagocytosis." (PMID 28894284, 2017). "The levels of CD33, a sialoadhesion expressed by monocytes and macrophages and recently shown to be associated with late-onset Alzheimer’s disease and the scavenger receptor CD36 varied between donors (1-74%, CD33; 8-89%, CD36)." (PMID 24341794, 2013). "Combined with the pleiotropic effects of inhibiting free fatty acid transport via CD36, these data provides a molecular mechanism through which amyloid-β can contribute to the nitric oxide signaling deficiencies associated with Alzheimer's disease." (PMID 21203512, 2010). "Moreover, alterations in CD36 expression have been implicated in numerous brain disorders, such as major depressive disorder and Alzheimer’s disease." (PMID 36310155, 2022). "Based on our observation that Aβ impairs the fatty acid translocase activity of CD36, the accumulation of vascular-associated Aβ in Alzheimer's disease could cause a local functional CD36 deficiency by blocking lipid and, potentially, oxidized lipoprotein uptake via this receptor." (PMID 21203512, 2010). "Early studies on Alzheimer’s Disease patients showed that CD36 is highly expressed in cortical samples of AD patients and cognitively normal subjects with the presence of amyloid plaques compared with amyloid-free controls." (PMID 35419363, 2022). "In contrast, triggering receptor expressed on myeloid cells 2 can regulate C/EBPα-dependent CD36 expression and subsequent Aβ phagocytosis to prevent Alzheimer’s disease." (PMID 36611964, 2022). "The role of CD36 in the amyloid-beta (Aβ)-induced microglial activation in Alzheimer's disease has been extensively investigated, but there has been no report so far of its role in prion diseases." (PMID 22292032, 2012). "Our approach to investigate the role of CD36 in the PrP106–126-induced microglia activation derived from consideration of its well-documented role in other protein misfolding-diseases such as Alzheimer's disease." (PMID 22292032, 2012). "Furthermore, in Alzheimer's disease, triggering receptor expressed on myeloid cells 2-induced overexpression of CD36 improved microglia phagocytosis of Aβ." (PMID 39691192, 2024). "Microglia cell CD36 for β-amyloid uptake also boosts pro-inflammatory response and may contribute to the pathogenesis of Alzheimer's disease." (PMID 22287954, 2012). "As increased lipoprotein oxidation and accumulation of lipid peroxidation products have been reported in Alzheimer's disease, we investigated whether β-amyloid altered oxidized lipoprotein clearance via CD36." (PMID 15546489, 2004). "In addition,CD36 was found to be involved in β-amyloid-induced ferroptosis in Alzheimer’s disease." (PMID 38218337, 2024). "In glaucoma and other neurodegenerative diseases, such as Alzheimer’s disease, microglia, as resident immune cells in the central nervous system, can mediate neuroinflammation; recognize and bind Aβ through membrane receptors, especially CD36; and exacerbate pathological progress." (PMID 36611964, 2022). "Increased CD36 gene expression following blood-brain barrier damage and circulating amyloid β protein following ischemic insult might contribute to the pathogenesis of vascular dementia and bridge the gap between vascular dementia and Alzheimer's disease." (PMID 27446928, 2016).
Alzheimer disease (continued). "The present study employed detailed psychological characterization of patients with Alzheimer’s dementia and dementia-related conditions in combination with complete sequencing (NGS) of a selected “candidate” gene (CD36)." (PMID 35768560, 2022). "Recognizing that Aβ inhibits NO signaling by suppressing sGC activity through CD36 and CD47 may clarify Aβ's role in Alzheimer's disease pathogenesis and could lead to novel therapeutics aimed at limiting the adverse effects of Aβ in the brain." (PMID 21203512, 2010).
glioblastoma (28 papers, 2017 to 2025). The most malignant astrocytic tumor (WHO grade IV). "CD36 has been implicated in the promotion of primary tumor proliferation and disease progression in multiple malignancies, including ovarian, glioblastoma, and breast cancers." (PMID 35008415, 2022). "In summary, the upregulated expression of CD36 plays an important role in the mediation of stemness in CSCs, such as oral, ovarian, and glioblastoma CSCs, and is associated with the cancer metastasis." (PMID 34603046, 2021). "Its mapping of co‐expression combinatorics and its finding of a CD44+/CD133+/ITGA6+/CD36+ molecule signature on gliomaspheres is a relevant step towards a more complete understanding of stemness‐associated molecules in glioblastoma." (PMID 30467961, 2019). "It has been suggested that CD36 regulates glioblastoma cell migration and proliferation, and preliminary data indicate that low CD36 levels in glioblastoma patients may be associated with a better prognosis." (PMID 37803478, 2023). "In addition to changes in Mmps, we also found that glioblastoma was associated with an increased expression of mRNAs encoding microglial phagocytic receptors—Cd93, Msr1, Cd36, Olr1, Megf10, Clec7a, and Scarf1." (PMID 32299465, 2020). "For example, in glioblastoma, CD36 overexpression in cancer stem cells promotes cancer progression, while endothelial CD36 expression exerts antiangiogenic and proapoptotic effects." (PMID 41267927, 2025). "Overall, patient blood-derived EV marker profiles were constant, but individual EV populations were significantly increased in disease compared to healthy controls, e.g. CD36+EVs in glioblastoma and GALC+EVs in multiple sclerosis." (PMID 37803478, 2023). "CD36 also plays a scavenger receptor role and regulates cancer stem characteristics in glioblastoma." (PMID 36008842, 2022). "For example, in glioblastoma, the elevated expression of CD36 promotes the growth of CSCs and helps CSCs to maintain stemness." (PMID 34603046, 2021). "Consistent with data using a specific small molecule CD36 inhibitor, 2-methylthio-1,4-napthoquinone (MTN), in glioblastoma stem cells, inhibition of CD36 with SSO is associated with a decrease in activation of pAkt." (PMID 32850342, 2020). "2-Methylthio-1,4-naphtoquinone (2M14NQ), a unique sulfur-containing quinone, which inhibits CD36 activity, decreases self-renewal ability and induces apoptosis in glioblastoma CD133+ CSCs." (PMID 32028963, 2020). "Next, to assess the potential clinical importance of the core 4‐marker signature identified (CD44, CD133, ITGA6 and CD36), we analysed publicly available glioblastoma gene expression and survival datasets from the TCGA." (PMID 30467961, 2019). "CD36 has been reported on glioblastoma cells as well, in a specific subset of stem-like cells, with role in stemness preservation and tumour initiation." (PMID 30069479, 2018). "In glioblastoma, CD36 is highly expressed in the self-renewing tumorigenic cancer stem cells, and activation of CD36 by its ligand, oxidized phospholipids, enhances cell proliferation." (PMID 30573731, 2018). "Inhibition of CD36 by 2-methylthio-1,4-naphthoquinone treatment decreases self-renewal and induces apoptosis of CSCs in glioblastoma." (PMID 29907133, 2018). "On the other hand, CD36 can express in cancer stem cells or tumor initiating cells (TICs), promoting glioblastoma progression or metastasis of breast, oral, and skin cancers." (PMID 28186980, 2017). "CD36 plays a protumor role in glioblastoma cancer stem cells." (PMID 38276607, 2024). "Importantly, data normalization improved the identification of disease-specific markers, such as CD36+EVs in glioblastoma and GALC+EVs in multiple sclerosis, which were significantly higher in disease compared to healthy controls." (PMID 37803478, 2023). "CD36 is enriched in CSCs from glioblastoma and functionally distinguishes self-renewing cells." (PMID 32028963, 2020).
glioblastoma (continued). "Theoretically, it might be that after all these experiments, cells with the CD44+/CD133+/ITGA6+/CD36+ signature can indeed be described as a phenotype especially characteristic of stem‐like glioblastoma cells." (PMID 30467961, 2019). "Finally, we investigated the relation of the identified CD44+/CD133+/ITGA6+/CD36+ signature to the four glioblastoma molecular subtypes (mesenchymal, neural, proneural, and classical) as well as the isocitrate dehydrogenase 1 (IDH1) status." (PMID 30467961, 2019). "Indeed, the expression of CD36 has been demonstrated to be increased in human tumour cell lines, human biopsies from ovarian tumours, gastric cancer, glioblastoma, and oral squamous carcinoma." (PMID 30069479, 2018). "Additionally, CD36 has pro-tumorigenic and progression properties in glioblastoma stem cells." (PMID 32850342, 2020). "CD36 is a key receptor involved in lipid uptake and scavenger receptor for oxidized lipoproteins, involved in TAM generation in low-grade glioma and glioblastoma multiforme." (PMID 35054787, 2022). "Given the combined action of CD36 and CD47, a compound interfering with both receptors (VT1021, a cyclic pentapeptide) was tested for safety in solid tumors, including glioblastoma." (PMID 35054787, 2022). "Hence, CD44+/CD133+/ITGA6+/CD36+ is the core signature that is consistently present in all seven gliomasphere systems as the common consensus multi‐marker combination – irrespective of the origin of the gliomasphere (stem‐like cell line, traditional glioblastoma cell line or patient‐derived)." (PMID 30467961, 2019). "Targeting both CD47 and CD36 simultaneously has led to the development of dual inhibitors like VT1021, a cyclic pentapeptide currently being evaluated for safety in solid tumours, including glioblastoma." (PMID 41195773, 2025). "However, CD36 expression was significantly higher in adrenocortical carcinoma (ACC), glioblastoma multiforme (GBM), KIRC, acute myeloid leukemia (LAML), and LIHC than in adjacent normal tissues." (PMID 34234847, 2021). "It has been shown that CD36, ITGA6, and CD133 are co-expressed in glioblastoma, and CD36 may be used to functionally distinguish CSCs from non-CSCs." (PMID 29907133, 2018).
lung carcinoma (27 papers, 2012 to 2026). "Hypermethylated CD36 caused cell cycle arrest, induced apoptosis, and inhibited cell migration in lung cancer cells which influenced proliferation." (PMID 41550652, 2025). "Our data suggest that CD36 deficiency greatly reduces lung cancer progression and that the protective effect of pitavastatin on lung cancer is impaired in CD36−/− mice." (PMID 38319449, 2024). "Additionally, CD36 is also associated with the functional impairment of immune cells in the lung cancer tumor microenvironment." (PMID 39744129, 2024). "Therefore, we used global CD36-deficient (CD36−/−) mice for determining the protective role of pitavastatin in lung cancer." (PMID 38319449, 2024). "Altered expression of CD36 in lung tissue is associated with lung cancer." (PMID 32357415, 2020). "In lung tissues, altered expression of CD36 is associated with lung cancer." (PMID 30127774, 2018). "Especially RosetteSepTM, both the human CD45 depletion cocktail and the CTC enrichment cocktail containing anti‐CD36, is widely used for culturing CTCs in lung cancer as well as other cancer types." (PMID 39105395, 2025). "In the analysis of human tumors, single-cell sequencing data from breast and lung cancers revealed that CD36 is predominantly expressed on TAMs, and that these TAMs have significantly higher expression of CD36 compared with control tissues." (PMID 39742252, 2024). "Fatty acid translocase (CD36) is overexpressed in many examined lung cancer cells, including PC9, HCC827, and H441 cells." (PMID 36293388, 2022). "CD36 overexpression has been reported to inhibit cell cycle arrest at the G0/G1 phase in lung cancer cells and promotes lung cancer progression; and CD36 inhibitors have a significant inhibitory effect on the growth of lung tumors." (PMID 36111143, 2022). "Major vault protein (MVP), implicated in the regulation of cellular signaling cascades and multidrug resistance, has been shown to interact with IFNgamma-regulated gene (CD36) in the H65 lung cancer cell model." (PMID 22384118, 2012). "In the context of lung cancer, CD36 facilitates tumorigenesis through multiple pathways, including the remodeling of tumor cell lipid metabolism, reprogramming of tumor-associated macrophages, and modulation of immune cell functions such as those of Tregs and CD8+ T cells." (PMID 41595136, 2026). "Consequently, we clearly demonstrate that inhibition of CD36 protein expression can mitigate HFD-accelerated lung cancer." (PMID 38319449, 2024). "Interestingly, our findings align with previous reports indicating that the re-expression of silenced CD36 inhibits the proliferation, migration, and invasion of lung cancer cells, arresting the cell cycle at the G0/G1 phase." (PMID 38293522, 2024). "used a CD14+CD36+PANK+ macrophage-lung cancer fusion hybrid signature, developed through a combination of FACS isolation and RNA-seq, to assess whether macrophage-cancer cell fusion hybrids could be found in peripheral blood of patients with lung cancer." (PMID 37427108, 2023). "Similarly, when CD36+CD14+PANK+ subpopulations isolated from lung-cancer patients were injected into mice, these cells were also found in spleens after 28 weeks, along with unstructured morphology and high levels of TTF-1." (PMID 37427108, 2023). "Cell cycle analysis in our study revealed that CD36 deficiency induced a decrease in population at S phase and an increase in population at G0/G1phase in C2C12 cells, which was consistent with previous study in lung cancer cells." (PMID 36111143, 2022). "We hypothesize that CD36 could provide a connection between lung microbiota and particulate insults that contribute to lung cancer development." (PMID 30127774, 2018). "However, the expression levels of CD163, CD169, CD204, CD64 and CD36 were significantly higher in SSc-ILD than in lung cancers." (PMID 29562615, 2018). "It was shown that the Src/PI3K/AKT axis is involved in CD36-mediated HCC and lung cancer development." (PMID 38319449, 2024).
lung carcinoma (continued). "ACADL, CD36, LPL, and MMP1 were the signature genes in the PPAR pathway that were identified to be shared among IPF and lung cancer." (PMID 33046043, 2020). "In lung cancer, increased methylation of CD36 promotes cancer progression, whereas decitabine and chidamide synergistically inhibit the growth of lung tumor; these findings indicate that CD36 demethylation might represent a potential strategy for tumor therapy." (PMID 31410189, 2019). "For instance, the protein-coding genes CD36 and TMPRSS4 were already identified as potential therapeutic targets of lung cancer, while TMPRSS4 can induce cancer stem cell-like properties in lung cancer." (PMID 30453959, 2018). "Hence CD36, may be important in the development of lung cancer." (PMID 22384118, 2012). "In fact, CD36 overexpression on H460 lung cancer cells increased the ratio of THCs formation, whereas no significant increase was reported when monocytes overexpressed CD36." (PMID 39967663, 2025). "Analysis of CD36 expression patterns within the NSCLC tissues that harbor microbial insults can provide the link between patient inflammatory molecules and microbes in lung cancer patients." (PMID 30127774, 2018). "Furthermore, the THC-specific cell surface signature (CD36+CD14+PANK+) enables the identification of these cells in matched primary tumour tissues and metastases, as well as in the bloodstream of patients with lung cancer, acting as a biomarker." (PMID 39967663, 2025). "However, high expression of ADAMTS8, CD36, DPYSL2, PLEKHH2, STX11, and TCF21 tends to lead to better prognosis, which coincides with the difference in expression of these HUB genes in normal samples and lung cancer samples." (PMID 37409245, 2023). "The results showed that the expression of MMP9 and MMP12 in lung cancer tissues was higher than that in normal tissues adjacent to cancer, and the expression of CD36 and FABP4 in lung cancer tissues was lower than that in normal tissues adjacent to cancer." (PMID 37978381, 2023).
Hyperinsulinemia (24 papers, 2012 to 2025). An increased concentration of insulin in the blood. "Hyperinsulinemia is suggested to facilitate permanent relocation of CD36 to the sarcolemma, which can cause an oversupply of FA to the cardiomyocytes." (PMID 34940639, 2021). "CD36 was found to be directly linked to the development of hepatosteatosis under conditions of elevated FFAs or hyperinsulinemia." (PMID 32796572, 2020). "An increased amount of CD36 in the hepatocytes’ plasma membrane was also observed in obese rats in association with its translocation induced by hyperinsulinemia." (PMID 32796572, 2020). "Prolonged sucrose consumption and hyperinsulinemia also cause CD36 upregulation in the liver." (PMID 32796572, 2020). "We provide compelling evidence for the role of the hyperinsulinemia in promoting resistance of CD36 to lipid regulation in the MetS mouse model." (PMID 26727015, 2016). "Our data provide several lines of evidence to support the interpretation that hyperinsulinemia and especially postprandial hyperinsulinemia counteracts lipid-induced CD36 down-regulation resulting in its dysfunctional response to dietary fat." (PMID 26727015, 2016). "Our data suggest a direct and sufficient role for hyperinsulinemia in Pparγ-mediated enhancement of hepatic Cd36 expression and thus the subsequent development of hepatosteatosis." (PMID 26085100, 2015). "Together, these findings provide evidence that hyperinsulinemia, by stimulating hepatic Cd36 expression, promotes hepatosteatosis in vivo." (PMID 26085100, 2015). "Hyperinsulinemia is a potential factor inducing CD36 expression in this situation." (PMID 32796572, 2020). "In addition, there was a negative correlation between the level of insulinemia 1 h after the gavage and that of postprandial CD36 suggesting a role of postprandial hyperinsulinemia in the impaired lipid response of intestinal CD36 in MetS mice." (PMID 26727015, 2016). "Insulin was demonstrated to counteract lipid-mediated CD36 ubiquitination and degradation, so we examined if the hyperinsulinemia observed in MetS mice after a lipid load, could be responsible for the absent response of CD36 to dietary lipid." (PMID 26727015, 2016). "In conclusion, the postprandial hyperinsulinemia observed in MetS mice alters post-translational regulation of jejunal CD36, which, in turn, interferes with the adaptive increases in gene expression important for optimization of TRL synthesis in the proximal intestine." (PMID 26727015, 2016). "Our data show that this diet induced MetS rodent model, results in a defect of lipid sensing by CD36 that might be consequent to the ambient hyperinsulinemia." (PMID 26727015, 2016). "In CD36-null mice, diet high in fructose induced markedly glucose intolerance and hyperinsulinemia." (PMID 23249574, 2012). "Absence of CD36 sensing was due to the hyperinsulinemia in MetS mice." (PMID 26727015, 2016). "Hyperinsulinemia is related to an up-regulation of SREBPs, which could conflict with our results, but we previously showed that SREBP2 controls the expression of some LDL receptor genes, such as CD36 gene expression." (PMID 22828168, 2012).